ENSG00000260851 (novel protein)
Gene: Protein-coding gene on chromosome 16 (66,469,812 to 66,517,312, reverse strand). Ensembl gene ENSG00000260851.
Genetic constraint (gnomAD): Missense variants: 54 observed, 61.87 expected, observed/expected ratio (o/e) 0.87, 90% interval 0.7 to 1.1. Synonymous variants: 16 observed, 20.44 expected, observed/expected ratio (o/e) 0.78, 90% interval 0.53 to 1.19.